ERCC6 (ERCC excision repair 6, chromatin remodeling factor)
Diseases named in the same sentence as ERCC6 in open-access papers (continued):
Sharing a sentence is not in itself a finding about the gene and the disease.
neurodevelopmental disorder (1 paper, 2017). A behavioral and cognitive disorder with onset during the developmental period that involves impaired or aberrant development of intellectual, motor, or social functions.
ERCC6 also shares sentences with these, for which no sentence is quoted: microcephaly (4 papers); progeria (3); deafness (2); prostate carcinoma (2); Werner syndrome (2); alcohol dependence (1); auditory neuropathy (1); autosomal recessive polycystic kidney disease (1); breast tumors (1); Cerebellar atrophy (1); cerebral palsy (1); chronic atrophic gastritis (1); cystic fibrosis (1); developmental delay (1); endometrial cancer (1); Ewing sarcoma (1); Fanconi anemia (1); growth failure (1); head and neck cancer (1); hearing disorder (1); hereditary neurodegenerative disorder (1); Hypertension (1); Leukoencephalopathy (1); liver cancer (1); metastasis (1); mucinous neoplasm (1); non-small cell lung carcinoma (1); nuclear cataract (1); retinopathy (1); spinal cord injury (1).
A further 3 diseases each share a sentence with ERCC6 in 1 paper.